GSTP1 (glutathione S-transferase pi 1)
Diseases named in the same sentence as GSTP1 in open-access papers (continued):
Sharing a sentence is not in itself a finding about the gene and the disease.
asthma (continued). "Glutathione S-transferase P1 (GSTP1) plays a role in a spectrum of respiratory diseases; however, the effects of sequence variation across the entire locus in asthma pathogenesis have yet to be determined." (PMID 18335111, 2008). "The GSTP1 114Val allele also had a suggestive association with increased risk of persistent wheezing, and TNF-308A with asthma and persistent wheezing (p < 0.05 unadjusted)." (PMID 18709160, 2008). "Age-stratified analysis of associations between SNPs of GSTP1, HMOX1, CAT, EPHX1 gene and asthma." (PMID 40433469, 2025). "The GSTP1 gene is located on a ‘hot spot’ site for asthma-related genes - chromosome 11q13." (PMID 36250015, 2022). "Mutation on GSTP1 does not have only direct effect to asthma symptoms but two-way gene-air pollution interaction between GSTP1 has the risk of childhood asthma." (PMID 30872977, 2019). "However, for example in a study on association of traffic-related air pollution with asthma, the GSTP1 slow activity genotype, as well as the GSTT1 null genotype, were found to be associated with increased risk for asthma, wheeze, and lowered lung function." (PMID 31649932, 2019). "The study suggests that interaction between GSTP1 and PM10 may alter the susceptibility to childhood asthma and buffers the harmful effects of air pollution." (PMID 30872977, 2019). "There is no or ignorable data on gene polymorphisms of GSTP1 and their role among asthma patients from Iraqi providence." (PMID 30872977, 2019). "Further, since SOD2 was associated with asthma, but GSTP1 was not, and MEHHP urine levels differ with genotypes of SOD2, we focused on the interplay of SOD2 and MEHHP with asthma." (PMID 28208751, 2017). "We investigated whether the GSTT1, GSTM1 and GSTP1 gene polymorphisms modified the associations between TRAP exposure during the first year of life and asthma, wheeze and hay fever in adolescence." (PMID 27043549, 2016). "GSTP1 rs1138272 and TNF rs1800629 SNPs were associated with asthma and wheeze, respectively." (PMID 24465030, 2014). "Supporting a role for Nrf2 in inflammatory allergic responses against airborne particles, polymorphisms in NRF2 and ARE-responsive antioxidant genes (GSTP1, SOD2) were associated with a trend toward increased risk of hospitalization during periods of high outdoor PM in an asthma/COPD cohort." (PMID 23766849, 2013). "DNA sequence variants in the GSTP1 Ile105Val locus, GSTM1 null, and GSTT1 null may contribute to susceptibility to oxidative stress and airway inflammation, which are key processes in asthma pathogenesis." (PMID 23357926, 2013). "The results of this study suggest that GSTP1, INSIG2 and IL4Ra may influence the lifetime asthma susceptibility through gene-gene interactions in schoolchildren." (PMID 22355322, 2012). "Maternal antioxidant gene polymorphisms (GSTP1 and GSTM1, GSTT1) have been regarded as specific risk factors for asthma in the offspring and may modify the relationship between prenatal acetaminophen exposure and childhood asthma." (PMID 22272211, 2012). "In this study, we did not observe significant associations of GSTM1 or GSTP1 polymorphisms with asthma either alone or in combination with NQO1 SNPs." (PMID 20049212, 2009). "Although GSTP1 is the GST enzyme most expressed in the lung, deficiency of two other GST genes, GSTM1 and GSTT1, has also been shown to influence the effect of passive smoking on the risk of childhood asthma and wheezing." (PMID 18709160, 2008). "A recently published study also showed that children with GSTP1 Val/Val genotype and a high activity for EPHX1 (microsomal epoxide hydrolase, also part of the antioxidative system) were at the highest asthma risk, especially if they lived < 75 m from a major road." (PMID 18709160, 2008). "Also, the presence of the GSTP1 homozygote Val/Val was less common in subjects with asthma than in control group." (PMID 17497028, 2007).
asthma (continued). "Haplotype analysis identified the GSTP1 GC combination as a risk haplotype (OR: 2.12, p = 0.025) and the CAT ATT haplotype as protective (OR: 0.45, p = 0.006), and MDR interaction modeling showed that rs1695 and rs7943316 together formed the strongest predictive model for asthma susceptibility." (PMID 41006975, 2025). "GSTs, including the isoforms GSTP1, GSTM1, and GSTT1, are multifunctional enzymes for cellular detoxification and are involved in oxidative stress pathways, among others, in the lung, and are associated, among others, with asthma and wheezing in children exposed to PTS or SHS." (PMID 32380770, 2020). "Interactive effects of variants in genes belonging to the GST family (GSTP1 Ile105Val, GSTM1 deletion) with levels of different outdoor air pollutants (e.g., NO2, ozone, and particulate matter PM10 and PM2.5) have been described for childhood asthma and traffic-related air pollution." (PMID 31921716, 2019). "However, a recent meta-analysis indicates that the GSTP1 single nucleotide polymorphism rs1695 did not affect the prevalence of asthma, suggesting that presence of GST variants contribute to airway diseases through interactions with the environment." (PMID 26490046, 2015). "The observed gene-pollution interaction between GSTP1 gene polymorphisms and exposure to PM2.5 and O3 could help us to understand the aetiology of asthma or wheezing, so allowing earlier prediction and diagnosis of childhood asthma/wheezing, and provide an efficient means of prevention." (PMID 23357926, 2013). "Previous studies have demonstrated that genes involved in oxidative stress response, including GSTP1, CAT, HMOX1, and EPHX1, participate in the pathogenesis of asthma." (PMID 40433469, 2025). "Gene-environment interactions between air pollution and SNPs in GSTP1 (rs1138272 and rs1695) and TNF (rs1800629) on asthma were investigated." (PMID 29246113, 2017). "The significant GxE interaction between GSTP1 rs1138272 and NO2 on asthma, which was identified in the pooled analysis, was identified by each GRS approach." (PMID 29246113, 2017). "The interaction between GSTP1 rs1138272 and NO2 was statistically significant in models for current asthma, ever asthma, and ever wheeze." (PMID 24465030, 2014). "A total of 2,743 children had complete data on asthma, wheeze, potential confounders, NO2, ozone, PM2.5, PM2.5 absorbance, and at least one SNP of interest (n = 2,367 with GSTP1 rs1138272; n = 2,559 with GSTP1 rs1695; n = 2,318 with TNF rs1800629)." (PMID 24465030, 2014). "Main genetic and environmental effect estimates for GSTP1, TNF, and NO2 for asthma and wheeze at school age (pooled data)." (PMID 24465030, 2014). "The three-way gene-gene interaction involves GSTP1 and INSIG2 characterize the obesity affects on antioxidative gene further influence asthma." (PMID 22355322, 2012). "Interactions of maternal oxidative stress genes (GSTM1, GSTP1, CAT, and MPO) with maternal prenatal exposure to air pollutants or tobacco smoke may contribute to asthma or allergic airway responsiveness." (PMID 22272211, 2012). "In conclusion, our study suggests that gene-gene interactions may occur between different pathophysiological pathways and a significant three-way gene-gene interaction between GSTP1, INSIG2 and IL4Ra on childhood asthma." (PMID 22355322, 2012). "We recognize that asthma is a complex disease, and studying only the GSTP1 gene does not provide a complete picture of genetic susceptibility." (PMID 18335111, 2008). "Although, the GSTP1-derived enzyme contributes more than 90% of GST activity, it has been found by many studies and confirmed by our finding that it protects children againstdeveloping asthma disease." (PMID 17497028, 2007). "It is also possible that intermediate metabolites, which are not metabolized or not excreted due to malfunction of GSTP1 may damage cells contributing to the pathogenesis of asthma." (PMID 30872977, 2019).
asthma (continued). "Earlier, in different association studies several asthma genes were identified in these regions, but none of them were confirmed later by GWAS, although two of them (PTGDR and GSTP1) were verified in candidate gene association studies in several independent populations." (PMID 22432035, 2012). "Different genotypes of the genes GSTM1, GSTP1, GSTT1, CYP1A1*2A and MPO also influenced the ratio between TDA in plasma and urine and therefore could predict a higher sensibility for isocyanate induced asthma in affected patients." (PMID 22016709, 2011).
colorectal cancer (49 papers, 2004 to 2025). A primary or metastatic malignant neoplasm that affects the colon or rectum. "Cox regression analysis confirmed the significance of both GSTM1-null and GSTP1 IleVal+ValVal (variant) genotypes as independent prognostic factors for increased overall mortality in patients with colorectal cancer." (PMID 38674199, 2024). "The combination of three GST genotypes, i.e., GSTM1 null, GSTT1 null, and GSTP1 Ile/Val or Val/Val genotypes, also demonstrated gene–gene interaction and further contributed to the increased risk of colorectal cancer." (PMID 39595582, 2024). "The obtained results resemble the results from the analysis using previous models, further highlighting the role of GSTM1 and GSTP1 polymorphisms as possible determinants of mortality risk in patients with colorectal cancer (HR 1.89, p = 0.001 and HR 1.50, p = 0.046, respectively)." (PMID 38674199, 2024). "Their findings suggest that GSTM1 and GSTT1 polymorphism and its combination with GSTP1 may be associated with colorectal cancer (CRC) susceptibility in the Naswar-addicted Pashtun population of Pakistan." (PMID 39595582, 2024). "Screening of genetic polymorphism of GSTP1 in colorectal cancer patients before chemotherapy could contribute to effectively decrease the occurrence of serious adverse toxicity, improve the predictive specificity for a severe event." (PMID 33280607, 2020). "Thus, the non-synonymous polymorphism of GSTP1 p.Ile105Val (c.313A>G in exon 5, rs1695), sometimes referred to as GSTP1*B, is considered as a risk factor in the early onset of neurotoxicity during the treatment of colorectal cancer with oxaliplatin." (PMID 32326111, 2020). "Screening of single-nucleotide polymorphisms of GSTP1 in colorectal cancer patients before chemotherapy may help to realize personalized therapy." (PMID 33280607, 2020). "Colorectal cancer patients with GSTP1 were found to show less positive responses than the GSTP1 deficient patients when treated with 5-fluorouracil (5-FU) or Oxaliplatin highlighting the role played by GSTP1 in drug resistance." (PMID 35582567, 2019). "We have recently reported that the GSTP1 polymorphism at codon 105 may be associated with superior overall survival in colorectal cancer patients." (PMID 15213713, 2004). "Though previous studies demonstrate the importance of NQO1 signaling for the progressive phenotype in colorectal cancer and GSTP1 is overexpressed in many cancers and linked to drug resistance, the molecular mechanisms of how these reductive enzymes involved in GBM proliferation remain unclear." (PMID 33087132, 2020). "However, when targeting the Caucasian population, we found that the TT genotype of GSTP1 rs1138272 may be positively linked to a decreased risk of colorectal cancer in Caucasians." (PMID 30740061, 2018). "The presented results confirm the increased expression of GSTP1 in colorectal cancer, which issimilar for NNMT." (PMID 41465541, 2025). "Overexpression of GSTP1 is widely observed in colorectal cancer, from aberrant crypt foci to advanced carcinomas." (PMID 35509845, 2022). "Polymorphisms in the genes of GSTP1, ERCC1, XPD, and TS were associated with overall survival in patients with refractory advanced colorectal cancer who received 5-FU/oxaliplatin combination chemotherapy." (PMID 15213713, 2004). "Meta-analysis studies did not confirm previous observations about a role for GSTP1 Ile105Val polymorphism in colorectal cancer susceptibility and the capability of GSTP1 Ile105Val polymorphism to confer any additional colorectal cancer risk." (PMID 31357662, 2019).
colorectal cancer (continued). "This study assessed potential relationships between GSTM1, GSTT1, and GSTP1 polymorphisms and colorectal cancer (CRC) risk in Polish nonsmokers." (PMID 29765533, 2018). "For GSTP1 I105V (rs947894), Val/Val homozygotes express lower enzyme activity and decreased clearance rate of chemotherapeutic compounds, which leads to an increased survival following 5FU/oxaliplatin treatment of colorectal cancer patients." (PMID 18547414, 2008). "In addition, a study of 107 patients with advanced colorectal cancer treated with a combination of 5FU and oxaliplatin were assessed for the GSTP1 I105V SNP." (PMID 14710198, 2004). "The genomic polymorphisms XPD-751, ERCC1-118, GSTP1-105, and TS-3′UTR may be useful in predicting overall survival and time to progression of colorectal cancer in patients who receive 5-FU/oxaliplatin chemotherapy." (PMID 15213713, 2004). "In addition the study supports the notion that the biotransformation enzymes GSTM1, GSTP1 and EPHX1 may modify the effect of dietary factors on the risk of developing colorectal carcinoma and adenoma." (PMID 18093316, 2007). "In addition, GSTP1 is known to detoxify platinum compounds, including oxaliplatin, a relatively new chemotherapy drug used in combination with 5FU for the treatment of advanced colorectal cancer." (PMID 14710198, 2004). "Mechanistically, one study have identified GSTP1 as a substrate of FBXO8-mediated ubiquitination, which suppresses malignant behaviors in colorectal cancer." (PMID 40375984, 2025). "However, in GSTP1, rs1695 was significantly associated with CRC risk in males, and rs1138272 showed a non-significant association with colorectal cancer risk." (PMID 39754630, 2025).
ovarian carcinoma (40 papers, 2010 to 2025). A malignant neoplasm originating from the surface ovarian epithelium. "Conducted multivariate logistic regression indicated that the expression level of lung resistance protein (LRP) and GSTP1 genes was a risk factor for primary epithelial ovarian cancer prognosis." (PMID 36422199, 2022). "The expression of GSTP1 in ovarian cancer tissue is studied mostly in association with other resistance proteins, especially MRP1 or lung-related protein." (PMID 36422199, 2022). "So far, miR-186 and miR-133b have been associated with reduced ovarian cancer drug resistance by silencing the expression of the drug-resistance-related proteins, GSTP1 and MDR1." (PMID 36422199, 2022). "We conducted the study to investigate the association between polymorphisms of ERCC1, XRCC1 and GSTP1, which responsible for platinum’s metabolisms in Thai epithelial ovarian cancer patients." (PMID 32711417, 2020). "Some important associations of ERCC1, XRCC1 and GSTP1 polymorphisms of clinical outcomes and adverse events in Thai epithelial ovarian cancer patients were noticed." (PMID 32711417, 2020). "As in previous reported, ERCC1, XRCC1 and GSTP1 polymorphisms had impacts on treatment responses of platinum based chemotherapy among epithelial ovarian cancer patents." (PMID 32711417, 2020). "Our results reveal that GSTP1 rs1695, known as a functional variant, is associated with both paclitaxel and carboplatin hematotoxicity, and the efficacy of ovarian cancer treatment." (PMID 30038720, 2018). "Possible increase of ovarian cancer risk was also shown for minor homozygotes of polymorphism p.Ile105Val in the GSTP1 gene (OR 1.73; 95% CI 0.92-3.26; p = 0.090)." (PMID 25591549, 2015). "Significantly increased risk of ovarian cancer in this group was also shown for minor p.Ile105Val homozygote in GSTP1 gene (OR 3.27; 95% CI 1.03-10.42, p = 0.044)." (PMID 25591549, 2015). "Thirty studies met inclusion criteria.Meta-analysis showed that the A allele of rs4680 in the COMTgene (OR 0.85; 95% CI: 0.73–0.99; P = 0.0373) andthe G allele of rs1695 in GSTP1 (OR 0.69; 95% CI:0.51–0.92; P = 0.012) were associated withreduced risk of ovarian cancer." (PMID 41158532, 2025). "Furthermore, the data on 6-fold-increased ovarian cancer risk in women carriers of combined “risk” genotypes (GSTT1-active/GSTP1*Ile) suggest a high probability of their synergetic risk effect on carcinogenesis in these women." (PMID 36422199, 2022). "Additionally, it seems that increased expression of GSTP1 in ovarian cancer is associated with non-coding RNA LINC00152 (LINC00152)." (PMID 36422199, 2022). "Genetic polymorphisms of ERCC1, and GSTP1 might be useful biomarkers for prediction of clinical benefit and toxicities of platinum-based chemotherapy in Thai epithelial ovarian cancer patients." (PMID 32711417, 2020). "Therefore, research to investigate the association of ERCC1, XRCC1 and GSTP1 polymorphisms with clinical treatment responses and adverse events from platinum-based chemotherapy especially in Thai patients with advanced epithelial ovarian cancer was needed." (PMID 32711417, 2020). "In ovarian cancer, high levels of GSH and glutathione S-transferase P1 (GSTP1) activity have been associated with resistance to cisplatin and carboplatin, although some conflicting reports exist." (PMID 40771481, 2025). "It has been discovered that platinum‐based medications are processed by GSTP1, which enables GSTP1 to be expressed in ovarian cancers." (PMID 37901797, 2023). "Among microRNAs investigated in ovarian cancer, which are shown to regulate GSTP1 gene expression, is miR-186." (PMID 36422199, 2022). "They demonstrated that GSTP1 has an important role in cisplatin and carboplatin metabolism in ovarian cancer cells and that inter-tumor differences in GSTP1 expression directly influence response to platinum-based chemotherapy in ovarian cancer patients." (PMID 36422199, 2022).